BRD4 (bromodomain containing 4)
Diseases named in the same sentence as BRD4 in open-access papers (continued):
Sharing a sentence is not in itself a finding about the gene and the disease.
tumor (continued). "The click-release PROTAC remained inactive in the absence of Tz but could be triggered upon exposure to Tz, resulting in intracellular BRD4 protein degradation and subsequent induction of tumor cell apoptosis." (PMID 38773495, 2024). "A recent example is the stimulation of anti-tumor immunity by BRD4 inhibition." (PMID 38302473, 2024). "One proposed tumor type, CNS tumor with BRD4::LEUTX fusion, has been described." (PMID 38500181, 2024). "Under ultrasound, ARV-MBs could play an effective antitumor effect by potentiating the ubiquitination and degradation of BRD4 in tumor." (PMID 39140036, 2024). "Compared to OPT-0139 used alone, the combination of cisplatin and OPT-0139 displayed a greater decrease in BRD4 expression and tumor cell viability; cell viability decreased by about 40% with the use of cisplatin alone and by almost 60% with the combined use of OPT-0139 and cisplatin." (PMID 38473320, 2024). "In preclinical studies, inhibition of BRD4 delayed FP-RMS xenograft tumor growth." (PMID 38916046, 2024). "Considering the differential expression of BRD4 between tumor and normal tissues, we further propose that t BET inhibition might serve as a potential alternative to conventional genotoxic agents like cisplatin, which induces non-specific DNA cross-links." (PMID 39301555, 2024). "Studies have demonstrated that PDL1 was a direct target of the ER BRD4 and the expression inhibition of BRD4 could promote anti‐tumour immunity by modulating PDL1 expression in epithelial ovarian cancer." (PMID 39323009, 2024). "Therefore, tumor types that are dependent on Brd4 for survival will likely be the ones more sensitive to Brd4 inhibition." (PMID 37049806, 2023). "In addition, the BRD4 inhibitor also regulates the characteristics of tumor cells, because BRD4 is also expressed in tumor cells." (PMID 37685868, 2023). "In vivo studies demonstrated that treatment with ARV-825 greatly suppressed tumor growth without causing harmful side effects and downregulated the BRD4-NUT expression level." (PMID 38130463, 2023). "Our case report confirmed that a new subgroup of CNS embryonal tumor with high aggressive potential, loss of H3K27me3 protein expression, BRDA4–LEUTX fusion, named “Embryonal CNS tumor with BRD4–LEUTX fusion”, has to be considered into the new CNS WHO classification." (PMID 36934287, 2023). "Moreover, Western blot analysis for tumor samples revealed a notable downregulation of BRD4 expression in the sh-LBX2-AS1-treated group compared to the control group." (PMID 37035213, 2023). "BRD4-driven oncogenes promote tumor cell proliferation, metastasis, and increased chemoresistance." (PMID 36793283, 2023). "Additionally, the numbers of metastatic lung nodules decreased significantly with combination therapy compared to either monotherapy, suggesting that the BRD4 inhibitor suppresses both local growth and systemic spread of the tumor." (PMID 37685868, 2023). "This is due to the spatiotemporal release of the BRD4 inhibitor JQ1 from ELJNV in a laser-light-controlled manner, which simultaneously causes antitumor immunity and blocks the PD-L1/PD-1 checkpoint to prevent tumor recurrence and metastasis." (PMID 37328484, 2023). "Overall, the expression of BRD4 in BET genes may play a key role in tumor development by participating in immune response." (PMID 36711038, 2023). "Among them, BRD4 is the most extensively studied in tumor research." (PMID 36793283, 2023). "BRD4 enhances tumor progression and induces EMT tumor cells." (PMID 36740668, 2023). "ARV-825 inhibited the overexpression of BRD4-NUT tumor growth in the 3T3 cell xenograft model." (PMID 38130463, 2023). "However, since we showed that BRD4 transcript levels (especially BRD4-L isoform) does not reflect well the BRD4 protein levels in tumors, thus the BRD4 overexpression status in tumor tissues should be evaluated using immunohistochemistry or proteomic methods." (PMID 37705995, 2023).
tumor (continued). "Notably, combination therapy delayed growth of the secondary tumor when compared to the control, RT-alone, and BRD4-alone groups." (PMID 37685868, 2023). "Bromodomain-containing protein 4 (Brd4) supports tumor-driving oncogene expression." (PMID 37924094, 2023). "Indeed, a previous study showed that BRD4 inhibition directly sensitizes tumor cells to RT by regulating DNA repair." (PMID 37685868, 2023). "Because our data demonstrated that the antitumor effects of the BRD4 inhibitor were accompanied by alterations in TAMs and MDSCs within the TME, the immunomodulatory effects of the BRD4 inhibitor may vary across tumor types." (PMID 37685868, 2023). "BRD4 inhibitor reduced the size of the unirradiated tumor, indicating that it may induce systemic immune responses." (PMID 37685868, 2023). "Importantly, combination treatment with local RT and the BRD4 inhibitor reduced tumor growth significantly more than either monotherapy alone." (PMID 37685868, 2023). "Importantly, expression of PD-1 on CD8+ and CD4+ T cells in tumor-draining lymph nodes increased upon combination therapy, indicating an abundance of tumor-specific T cells after local RT and BRD4 inhibition." (PMID 37685868, 2023). "Given the reciprocal activity of BRD4 with the YAP/TAZ complex, dual BRD4 and YAP/TAZ inhibition could potentially enhance therapeutic efficacy with respect to mechanosignaling‐associated properties of tumour cells." (PMID 37994501, 2023). "Therefore, further studies are needed to dissect the direct and indirect effects of BRD4 inhibition on tumor cells." (PMID 37685868, 2023). "To examine whether the addition of the BRD4 inhibitor improves systemic immune responses evoked by local RT, we used the dual-tumor model that was previously used to observe the abscopal effects of RT." (PMID 37685868, 2023). "Collectively, these results suggest that BRD4 inhibition may contribute to a systemic decrease in immunosuppressive cells, particularly MDSCs, and an increase in tumor-specific T cells in draining lymph nodes." (PMID 37685868, 2023). "Moreover, simultaneous introduction of our ENCTAC components also induce efficient tumor degradation of BRD4 with better effect as compared to the reference PROTAC compound of ARV-825 or the inhibitor JQ1." (PMID 36516252, 2022). "Alternatively, BRD4 inhibition might also inhibit immune surveillance, for example of oncogene-induced senescent cells during tumor development by preventing secretion of inflammatory cytokines." (PMID 36139513, 2022). "Knockdown of BRD4 resulted in attenuation of TNBC tumor growth in vivo." (PMID 36499487, 2022). "However, the effect of targeting BRD4 on chemoradiotherapy‐induced PD‐L1 expression in NSCLC tumour cells is poorly understood." (PMID 35083874, 2022). "Moreover, BRD4 expression positively correlated with a major tumour infiltration of B cells, CDT4+ T cells, CDT8+ T cells, macrophages, neutrophils and dendritic cells." (PMID 35267409, 2022). "The combination of Laser + PGDA7 NPs activated the caspase-3 protein in MDA-MB-231 tumour cells more efficiently than PDT (Laser + PGDA) or BRD4 degradation with PGDA7 alone, implying the improved apoptosis induction performance of PDT combined with BRD4 degradation in vitro." (PMID 35882867, 2022). "Likewise, we looked into HPV-positive HNSCC tumours with different grades in the TCGA and found that higher grade tumours appeared to have higher expression of BRD4, CDKNA2, RAD51AP1 and CDC6 with EGFR expression was lesser in higher tumour grades." (PMID 36333293, 2022). "A plausible explanation is the heterogeneity of BRD4 regulatory targets in different tumour types." (PMID 36309482, 2022). "In tumor cells, whether BRD4 can also regulate the SUMOylation level of the protein by regulating the expression of Senp1, this will be a direction worth exploring." (PMID 35402244, 2022).
tumor (continued). "As expected, the pH/GSH‐responsiveness significantly facilitated the release of dBET6 from the nanoparticles within the cells, which led to the efficient degradation of BRD4, inducing apoptosis of both cell lines and the inhibition of tumor growth both in vitro and in vivo." (PMID 35988145, 2022). "Both JQ1 and ARV-771 belong to BRD4 inhibitors, which may enhance chemotherapy sensitivity and anti-tumor immunity of chemoradiotherapy by reducing treatment-induced PD-L1 expression in NSCLC." (PMID 35628460, 2022). "In summary, our findings demonstrate that BRD4 is a potential tumor biomarker for EC." (PMID 35902869, 2022). "Free ARV771 displayed a negligible influence on BRD4 expression in tumour xenografts." (PMID 35882867, 2022). "In addition, pancreatic progenitor cell differentiation and proliferation factor (PPDPF), as well as Bromodomain-containing 4 (BRD4), can also enhance the repair capacity of tumor cells." (PMID 36139006, 2022). "Moreover, BRD4 inhibition has gained interest, in several tumour types, as a novel strategy to target oncogenic transcription factors aberrantly activated by super‐enhancers." (PMID 35182012, 2022). "Moreover, BRD4 inhibition synergized with chemoradiotherapy and PD‐1 blockade to show a robust anti‐tumour immunity dependent on CD8+ T cell through limiting chemoradiation‐induced tumour cell surface PD‐L1 upregulation in vivo." (PMID 35083874, 2022). "Furthermore, we found that knockdown of BRD4 in MDA-MB-231 cells with shRNA inhibited tumor growth in vivo." (PMID 36499487, 2022). "The up-regulation of BRD4 expression was found in RCC tissues, and associated with advanced histological stage and lymph node metastasis, while knockdown of BRD4 reduced cell vitality and inhibited tumor growth." (PMID 35918352, 2022). "Accordingly, the inhibition of the H3K27ac reader, the bromodomain-containing protein 4 (BRD4), with the small-molecule JQ1 reverted the bad prognosis-associated transcriptional program in HCC cells, and significantly reduced tumor burden in a mouse model of NASH-induced hepatocarcinogenesis." (PMID 33809263, 2021). "Although the mutations of BRD4 and STK11 were associated with tumor stage in this study, the low frequency of BRD4 and STK11 mutations suggests that the sample population may be too small to cause false positive." (PMID 33432021, 2021). "Because targeting Brd4 slows down tumor growth partially through downregulating Myc expression, we then investigated whether the downregulation of glucose transporter GLUT1 resulted from the reduced Myc expression in Brd4-/- CD8+ T cells." (PMID 34512660, 2021). "In addition, targeting Brd4 has shown great potential for tumor eradication by downregulating Myc expression, particularly in hematopoietic malignancy." (PMID 34512660, 2021). "Several studies demonstrated that miRNA-612 (miR-612) exerts tumor-suppressive effects through targeting multiple anti-apoptotic genes, such as bromodomain-containing protein 4 (BRD4), AKT serine/threonine kinase 2 (AKT2), and NIN1/PSMD8 binding protein 1 homolog (NOB1)." (PMID 34298879, 2021). "miR-1340 targets BRD3 and BRD4 to suppress tumor cell growth." (PMID 34540900, 2021). "Additionally, co-inhibition of RAC1 and BRD4 by JQ1+NSC treatment reduced MDA-MB-231-based tumor growth in vivo." (PMID 34803511, 2021). "Substantial evidence indicates that the primary target of most BETi, BRD4, is oncogenic—therefore identifying tumour types that are dependent on BRD4 for survival might be one way to identify those tumours that will be most sensitive to BRD4 inhibition." (PMID 33723398, 2021). "Both miR-214 antagonist and BRD4 inhibitor decreased the tumor severity in CTCL mouse models." (PMID 33628583, 2021). "We downloaded H3K4me1 (ENCODE, ENCFF557VIT) and BRD4 (GEO, GSM3593876) ChIP-seq data in HCT116, a CRC cell line, from public databases, and calculated the RPM values of H3K4me1 and BRD4 signal in significant CRC tumor enhancer loci." (PMID 34737287, 2021).
tumor (continued). "Diminished miR-29b reportedly induced the accumulation of tumor-promoting protein BRD4, which bound acetylated histones throughout the genome to regulate other tumor-related genes and highly activate IL-15 signaling, which, in turn, led to aberrant expression of miR-29b15." (PMID 33628583, 2021). "Moreover, BRD4 promoted tumor progression by inducing the expression of several oncogenes and immunomodulatory genes, including c-Myc24, PD-L128, and B7-H329." (PMID 33850096, 2021). "However, their efficacy has been limited by different factors, including an upregulation of BRD4 itself which follows the exposure to the drugs and hinders their anti-tumor activity." (PMID 36046113, 2021). "However, we corroborated the tumor-suppressive roles of insertions in Adk and Zbtb20 and in Nipbl, Pdlim5, Ppp1r12a, Tnrc6b, Brd4, Cul3, Ctnna3, Elavl1, Gphn, Nfia, Ptpn12, Taok3, and Rasa1." (PMID 33435458, 2021). "Its anti-tumor activity is further enhanced by the targeted inhibition of BRD4." (PMID 33051401, 2020). "Given that overexpression of both BRD4 and CAV-2 are observed in PC, targeting the BRD4-CAV-2 interaction by developed BET inhibitors may be applicable to prevent tumor growth in PC." (PMID 32099528, 2020). "Brd2 and Brd4 have been extensively studied in the context of cell-cycle control and transcription elongation and activation and are known to be overexpressed in multiple tumor types." (PMID 33015071, 2020). "In summary, our study demonstrated the anti-tumor effect of a BRD4 inhibitor in RCC." (PMID 32303673, 2020). "In HNSCC, overexpression of BRD4 is relevant to tumor aggressiveness and progression." (PMID 32961679, 2020). "Silencing of BRD4 also increased the sensitivity of the tumor cells to CHEK1 and PARP inhibitors." (PMID 33488950, 2020). "BRD4 could directly bind to miR-338-3p in MM cells and miR-338-3p exerted an anti-tumor role through targeting BRD4." (PMID 32782441, 2020). "Moreover, BRD4 mRNA expression was significantly higher in GC compared with the surrounding non-tumor gastric tissues in GEO GSE29272 and GSE79973 datasets." (PMID 32157097, 2020). "Our study may explain how tumor cells utilize the pro-oncogenic signals derived from inflammatory microenvironment and further clarify the working mechanism of Twist/BRD4 complex." (PMID 32528891, 2020). "Overall, BRD4 impacts tumor growth in NSCLC in both Myc-dependent and independent manners." (PMID 32793596, 2020). "In addition to reducing tumor growth, inhibition of both BRD4 and PI3K reduces the infiltration of myeloid-derived suppressor cells and stimulates antitumor immune responses." (PMID 32694708, 2020). "miR-338-3p and BRD4 were co-transfected into MM cells to explore whether miR-338-3p exerted an anti-tumor role in MM cells through targeting BRD4." (PMID 32782441, 2020). "Super‐enhancers exert a major role in the progression of various tumor types including PCa and also contribute to resistance mechanisms involving SE‐binding factors such as BRD4 or FOXP1." (PMID 32333502, 2020). "To further investigate whether interference with BRD4 could inhibit tumor growth in vivo, we constructed stable inhibition of BRD4 cell line in PANC-1." (PMID 32099528, 2020). "In addition, we detected BRD4 expression in normal and tumor tissues, and the results made clear that BRD4 expression in tumor tissues is undoubtedly higher than that in normal tissues." (PMID 33135348, 2020). "Following this report, BRD4 was demonstrated as an oncogene in many tumor types." (PMID 33488950, 2020). "These authors proposed an epigenetic explanation for BED inhibitor resistance in TNBC cells, whereby the PP2A tumour suppressor gene is inactivated, leading to hyperphosphorylated BRD4 which binds more strongly to MED1 and allows for bromodomain-independent chromatin recruitment." (PMID 31886177, 2019).
tumor (continued). "It has been shown that progerin may inhibit cell transformation by changing the distribution of the general transcriptional regulator BRD4 on chromatin and activating tumor-protective cellular pathways." (PMID 31156709, 2019). "Thus, it displaces BET bromodomains from chromatin, interfering with BRD4 function and leading to growth arrest and promotion of apoptosis in tumor cells." (PMID 31905936, 2019). "Subsequently, inhibiting or blocking the BRD4 protein from gaining access to acetylated histones may prevent the transcription of c-Myc and thus limit the proliferation of tumour cells." (PMID 31886177, 2019). "Additionally, xenograft tumor models further showed that the knockdown of BRD4 significantly suppressed tumor growth in vivo." (PMID 30784214, 2019). "In vitro assays indicated that BRD4 downregulation inhibited the proliferation of PCa tumor cells." (PMID 30784214, 2019). "Finally, in the present study, expression of the downstream oncogenic activator VEGF was upregulated by the SPZ1–TWIST1 complex through its interaction with BRD4 in tumor cells." (PMID 30154425, 2019). "Importantly, we show co-expression of hnRNPA1 with the BET protein BRD4 (Bromodomain-containing protein 4) in human tumor samples." (PMID 31480735, 2019). "Additionally, the levels of TRAF6, BRD4, and NFATc1 expression, IκB-α degradation, and p65 nuclear translocation were higher in blood mononuclear cells from tumor samples than in those from normal group at basal levels." (PMID 30455393, 2019). "BET family member bromodomain-containing protein 4 (BRD4) has been found to be highly expressed in OS tumor tissues and OS cell lines, and may play an important role in the development of aggressive OS9–11." (PMID 31653826, 2019). "Additionally, considering BRD4 linkage to MYC has been demonstrated in multiple disease settings, we examined the anti-tumor activity of AZD5153 in a MYC amplified (but also with BRD4 copy-number gain of 3) ovarian patient-derived xenograft, OV0452F." (PMID 30036377, 2018). "The association of BRD4 expression with T-bet+ TILs, and T-bet+ TIL-dependent disease-free survival suggests a potential link between BRD4-mediated tumor development and tumor immune surveillance, possibly through BRD4’s regulation of Jagged1 signaling pathways." (PMID 30029633, 2018). "Finally, we demonstrate the effectiveness of co-targeting of BRD4 and NRG1 signaling in the context of BRD4-amplified patient-derived tumor models." (PMID 30036377, 2018). "BRD4 is also involved in the regulation of the tumor‐suppressive immunosurveillance program." (PMID 29661909, 2018). "To test whether inhibition of NRG1 signaling could result in anti-tumor activity in BRD4-amplified HGSOC tumors, we employed lapatinib, an orally available tyrosine kinase inhibitor with activity against the HER pathway." (PMID 30036377, 2018). "Based on the positive associations observed between BRD4 expression, Jagged1 expression, and T-bet+ TILs, Jagged1, through BRD4 regulation, may also be important in mediating tumor-immune cell interaction." (PMID 30029633, 2018). "BRD4 enrichment was evident in 492 assigned genes in skeletal muscle from C26-tumor-bearing mice." (PMID 29167426, 2017). "To understand the role of BRD4 in transcriptional regulation of tumor-induced skeletal muscle wasting, we mapped the genome-wide distribution of BRD4 in skeletal muscles from control and C26-tumor-bearing mice treated with either (−)-JQ1 (20 mg/kg/day) or (+)-JQ1 (20 mg/kg/day) by ChIP-seq." (PMID 29167426, 2017). "Brd4 localizes on both active promoters and active enhancers in human and mouse tumor cells." (PMID 29263365, 2017).